CXCL10 (C-X-C motif chemokine ligand 10)
Diseases named in the same sentence as CXCL10 in open-access papers (continued):
Sharing a sentence is not in itself a finding about the gene and the disease.
infection (continued). "In addition, we also found that the expressions of CCL2, CXCL10 and IL-6 were significantly increased in the terminal stage of infection with RABV." (PMID 39273091, 2024). "Surprisingly, LNCaP cells express CXCL10 upon SFV-replicon particle infection independent of encoded transgenes, with detectable expression at 6 h, suggesting innate cellular induction." (PMID 38425844, 2024). "As in THP-1 cells, infection of MDM with Gag-LUC induced a robust type I IFN response leading to significantly higher expression of CXCL-10, IFIT-2 and MxA, as well as CXCL-10 protein compared to VSV-G pseudotyped LAI infection, all of which was reduced by ruxolitinib treatment." (PMID 38778414, 2024). "Of note, infection of Calu-3 cells with Omicron led to limited induction of IP-10/CXCL-10." (PMID 38568894, 2024). "Additionally, CXCL10 is upregulated, likely contributing to the recruitment of immune cells to the site of infection." (PMID 39591472, 2024). "Finally, we quantified the lung viral load by qPCR and found similar levels of SARS-CoV-2 N1 gene expression in infected Cxcl10+/+ and Cxcl10−/− mice at 4 days post infection." (PMID 39803542, 2024). "This may explain the relatively low presence of some of the cytokines we investigated at 24 hpi, including IFN-β and CXCL10, that may be dependent on infection or activation of astrocytes or pericytes." (PMID 40295794, 2024). "Histopathological damage, inflammatory gene induction and virus load in the lungs of male mice 4 days post infection and before death were not broadly influenced by Cxcl10 deficiency." (PMID 39803542, 2024). "Likewise, CXCL10 has been proposed as a biomarker to monitor the infection progression of the retroviruses human T-lymphotropic virus 1 (HTLV-1) and human immunodeficiency virus." (PMID 39452756, 2024). "Mice treated with CXCL10 had significantly more cells recruited into the lungs after infection." (PMID 39749186, 2024). "In addition, we found that CXCL10 was significantly upregulated in the last three stages after infection." (PMID 37211158, 2023). "Furthermore, qRT-PCR analysis of proinflammatory genes indicated significantly increased levels of Cxcl10, Il-1b, and Tnf, especially at 72 h post-infection." (PMID 37426673, 2023). "Interestingly, IL-6, which has been proposed to inhibit DC maturation, was only minimally secreted post LOAd732 infection in DCs and LOAd732 induced high levels of CXCL10 comparable to LOAd703." (PMID 37501121, 2023). "An important result of this study is that the intensity of the initial infection response to SARS-CoV-2 infection may be quantitatively assessed by the levels of both CXCL10 and amino acid catabolites." (PMID 38123556, 2023). "In contrast, BA.5 infection upregulated Cxcl10, Isg15, and Mx-1 expression more than the other Omicron subvariants infection in the lung periphery area, suggesting that BA.5 might provoke severe inflammation, supporting the histopathological data." (PMID 37488344, 2023). "Increased serum concentrations of TNF-α and CXCL10 have also been observed after the administration of one vaccine dose after a previous infection, which is of note because the serum CXCL10 concentrations are positively correlated with postvaccine antibody responses." (PMID 36851332, 2023). "However, Kalejta and colleagues went on to show increased IFNβ and CXCL10 transcripts in UL138-M16STOP infection in CD34+ HPCs, concluding that UL138 functions in immune evasion, degrading STING to abate a type-1 interferon response." (PMID 37289831, 2023). "However, the mRNA expression of CXCL10 in hPBDMs was only significantly induced (>50-folds) by T. marneffei infection, which peaked at 8 h post-infection." (PMID 37695039, 2023). "(E) CXCL10 concentration in the culture media 72 hr post-infection quantified by ELISA." (PMID 37073954, 2023).
infection (continued). "Furthermore, a prospective multicentre observational trial of 280 transplant recipients that used both SELDI-TOF–MS and ELISA on urine samples, concluded that CXCL10 levels were similar between patients that experienced either TCMR or infection." (PMID 37993798, 2023). "Similarly, in humans, high levels of CXCL10 are expressed by intestinal ECs in AIDS patients with active infection and symptomatic disease." (PMID 37110479, 2023). "Infection with virulent ASFV isolates often results in an exacerbated immune response, associated with elevated serum levels of pro-inflammatory cytokines (IL-1α, IL-1β, IL-6, TNF, CCL2, CCL5 and CXCL10)." (PMID 36680273, 2023). "We also observed another marker of inflammation, CXCL10, to be significantly associated with the diversity of genetically-intact HIV, and this marker had a positive association with the infection frequency of genetically-intact HIV proviruses in the co-infected individuals." (PMID 35916523, 2022). "Unlike HSV-1, CXCL10 was found to promote the infection caused by stimulating virus replication in immune cells during herpes simplex virus type 2 (HSV-2) infection." (PMID 36366543, 2022). "It is, therefore, conceivable that CCL-4, CCL-5, CXCL-10 and IL-8 would initiate and maintain the inflammatory response in the acute phase of infection and the increased release of CCL-2 during the convalescent phase would regulate the immune response in order to reduce immune pathologies." (PMID 35543881, 2022). "Finally, a high number of pro-inflammatory cytokines were up-regulated upon infection, such as CXCL10, CCL5, CXCL11, TNF, CCL3, CXCL8, and IL6." (PMID 35893684, 2022). "Additionally, IFN-γ, which is essential for the expression of CXCL9 and CXCL10 by macrophages and several cell types during the recruitment of T-cells at the site of infection, is produced to enhance host protection." (PMID 36189358, 2022). "However, at 4 h post-infection, levels of Cxcl10 and Ccl7 started to increase, also in the presence of TAT-I24." (PMID 35806257, 2022). "Furthermore, in vitro studies indicated that astrocytes respond to infection by upregulating CXCL10 mRNA expression and releasing CXCL10 into the supernatant, which is completely abolished by CXCR3 antagonists." (PMID 35702353, 2022). "In addition, no significant alteration in the levels of IFNγ, IL-1β, IL-4, IL-6, IL-8, IL-10, CXCL10, and TNFα was observed in peripheral blood after Vir-S74-T3Bo infection by comparing Att-S74-T3Bo-inoculated and naïve control animals." (PMID 36466866, 2022). "Next, PAMPs trigger the production of several proinflammatory cytokines and chemokines, including TNF, IL-6, type-1 IFN, CCL2, CCL3, CCL4, and CXCL10 (IFN-γ-induced protein 10 kDa [IP-10]), which lead to the recruitment of monocytes, macrophages, and T cells to the infection sites." (PMID 35464491, 2022). "Indeed, cytokine profiling revealed a vaccine dose-dependent reduction of infection-induced inflammatory C-X-C motif chemokine ligand 10 (CXCL10) and 11 (CXCL11) in both serum and BAL compared with non-vaccinated controls." (PMID 35479095, 2022). "Increased concentrations of CCL2/MCP-1 and CXCL10/IP-10 resulted in an augmented recruitment of monocytes to infection sites and, consequently, might generate cells more susceptible to CHIKV infection." (PMID 35456119, 2022). "CXCL10 may, however, also be released in the context of other treatment-related infections, particularly those of the gut." (PMID 36142860, 2022). "The expression of these cytokines, including CXCL10, as shown in NiV-infected primary endothelial cells in vitro, could promote the induction of functional monocytes and T cell movement to the site of infection." (PMID 35744680, 2022). "Notably, levels of CXCL-10 after RV16 infection were similar for both cRG-I groups on d3 while the influx of immune cells into the nasal compartment, in part a response to CXCL-10 release, was faster and higher in the 1.5 g/d group." (PMID 36296939, 2022).
infection (continued). "The cytokines retrieved from M9809 gene set of Molecular Signatures Database in Gene Set Enrichment Analysis (GSEA), such as IL-7, CCL2, CXCL10 and IFNs, were significantly up-regulated in cerebral cortex, but markedly down-regulated in cerebellum and right ventricle post infection." (PMID 35377064, 2022). "In addition to TNF-α, CXCL10 (one of the top five hub genes), and CCL5, two chemokines also found to be the hallmarks of the inflammation caused by LgyLRV1+ infection were also found to be present in the 8h_bisque4." (PMID 35992159, 2022). "In our study, the control ΔM063R infection similar to the wildtype virus did not cause upregulation of CXCL10 in human CD14+ monocytes." (PMID 36103568, 2022). "G-614G infection of NPOs and BOs significantly increases CXCL10 at 72 hpi." (PMID 36496442, 2022). "The CXCL10/CXCR3 axis plays a crucial role in disease pathogenesis upon CVA2 infection." (PMID 35604176, 2022). "Interestingly, IFNG was strongly expressed in VAT in the SIV+ART+ group, as were TNFA and CXCL10—suggesting that the duration of infection and/or ART significantly impacted the type II IFN pathway as well." (PMID 36231066, 2022). "The increased release of TNF-α, IL-23, CCL2, CXCL8, and CXCL10 by sc1o-treated MdMs may contribute to a pro-inflammatory environment at the infection site and thereby promote the immune response against pathogens via several mechanisms." (PMID 33330947, 2021). "Furthermore, influenza virus has been shown to induce rapid the expression of CXCL9 and CXCL10 following infection in epithelial cells." (PMID 34179166, 2021). "Interestingly, neuropathic strains of EHV-1 have been shown to selectively stimulate CXCR3 ligands CXCL9 and CXCL10 production by the respiratory epithelium to facilitate attraction and infection of CD4, CD8, and monocytic CD172+ cells." (PMID 34179166, 2021). "Along with this observation, we also observed significantly lower levels of IL-6, IFN-γ, and CXCL-10 24 h post-infection, IL-17A and TNF-α 4 days post-infection, and IL-1β, CCL2 and CCL5 7 days post-infection in the lung of IL-38-treated mice, compared with mice without IL-38 administration." (PMID 33414457, 2021). "In addition, the 040417 strain reduced the production of CXCL8 at the two times points evaluated and diminished the levels of CCL5 and CXCL10 at hour 72 post-infection." (PMID 34064210, 2021). "Our data showed that, upon successful infection, CXCL10 and IFI44L were induced in a virus-specific manner despite ethnicity and that the level of induction was strongly correlated with the norovirus RNA copy number at the transcriptomic level and was comparable between two virus strains." (PMID 33494515, 2021). "Similar to the “cytokine storm”, inflammatory chemokines like CXCL9 and CXCL10 are likely important to mount an effective immune response to the parasite early during the infection, but may be detrimental under certain circumstances." (PMID 33407502, 2021). "Furthermore, the top six DEGs, including CSF3, CCL2, CCL7, IL6, CXCL11, and CXCL10, were all upregulated after infection at P3." (PMID 34026883, 2021). "In addition, another recent study showed that there was significant upregulation of CXCL10/IP-10 in secondary infection due to the dengue virus compared to the other cytokines analyzed." (PMID 34578370, 2021). "To summarize, the abnormal expression of CXCL10, ICAM1, CD40, IRF7, and B2M may be the main cause of tracheal dysfunction after infection with coronavirus." (PMID 34504502, 2021). "Nevertheless, our results are consistent with a molecular mechanism of reduced CXCL10 cleavage by L. (V. ) panamensis contributing to greater T cell migration, which may result in increased inflammation and cytotoxicity during infection." (PMID 34710089, 2021). "At early stages of infection, the parasite can reduce CXCL10 secretion." (PMID 34381047, 2021). "Patient PBMCs also exhibited significantly decreased CXCL10 levels in response to infection." (PMID 34625101, 2021).
infection (continued). "Moreover, macrophages presented the earliest and strongest transcriptional response to the infection, primarily responding to intracellular viral RNA with pro-inflammatory cytokines such as CXCL10, CCL2, and others." (PMID 34381043, 2021). "Thus, many immune related proteins are elevated at infection in both cases, such as chemokine ligand 10 (CXCL10), interferon gamma (IFNG), interferon lambda 1 (IFNL1) and chemokine ligand 8 (CCL8)." (PMID 34844191, 2021). "In addition, patients with acute toxoplasmosis showed significantly higher plasma levels of CCL4, CXCL9, and CXCL10 than patients in the chronic phase of infection or HDs." (PMID 34607465, 2021). "However, upon comparing the chemokine profile of the three hCoVs, it can be concluded that CCL2/MCP-1, CXCL8, and CXCL10/IP10 have vital roles in the pathogenesis of infection and serve as prognostic markers for hCoVs’ severity." (PMID 34046036, 2021). "Increased expression of CCL5 and CXCL10 could enhance recruitment and activation of immune cells and resident neuronal cells at the site of infection, thereby promoting the clearance of free virus as well as of infected cells in the CNS." (PMID 33407600, 2021). "CXCL10 protein is also secreted into the blood stream from lung tissues after IV infection." (PMID 33627703, 2021). "Interestingly, IFNγ, a major inducer of CXCL10, was upregulated following infection of Calu-3 cells, but was still at relatively low levels." (PMID 34205098, 2021). "It has been reported that the infection with SARS-CoV-2 can cause a cytokine storm in patients with symptoms severe or critical, consisting of an increase of IL-1β, IL-4, IL-6, IL-10, IL-17, TNF-α, G-CSF, GM-CSF, IFN-γ, CCL2, CXCL8, and CXCL10." (PMID 33917837, 2021). "Furthermore, expression of chemokine genes Ccl3, Cxcl2 and Cxcl10 also significantly increased in migratory ILCs after STM infection." (PMID 33414524, 2021). "In addition, we discovered that ASFV infection is involved in the regulation of chemokine expression in PAMs, and the chemokines, such as C-X-C motif chemokine 8 (CXCL8) and CXCL10, were upregulated after infection." (PMID 34412678, 2021). "Moreover, data showed that LP17 not only abrogated the significant difference in IL1β and TNFα expression, but also eliminated the apparent difference in CCL2 and CXCL10 expression between both groups of S. typhimurium-infected mice at 3 days post-infection." (PMID 33475464, 2021). "This inference from modeling cellular infection is consistent with previous observations that C. trachomatis suppresses levels of chemokines including CXCL10 in A2EN endocervical epithelial cells by unknown mechanisms." (PMID 33106516, 2020). "Although the striking increase in the expression of CXCL10 in bats is at odds with the outcome of infection in human patients, it may hint at a protective role in bats." (PMID 32226041, 2020). "We conclude that viral DNA is the active PAMP and this notion was also supported by the observation that mutation D185E in the RT active site (HIV‐1 ∆CA‐SP1 RT D185E) also reduced activation of IFIT‐1 luc expression and CXCL10 secretion on infection of the THP‐1 IFIT‐1 reporter cells." (PMID 32852081, 2020). "Notably, the mRNA levels of Tnf, Il6, Il1b, Cxcl10, and Cxcl5 were significantly increased and that of Il10 decreased in lung tissue from Ppara-/- mice, compared with Ppara+/+ mice, during Mabc infection." (PMID 32155958, 2020). "Like IFNβ, CXCL10 expression was only elevated by phosphodiesterase mutation when pde2 alone was targeted, not after infection with the Δpde1 or Δpde1Δpde2 pneumococci." (PMID 32300347, 2020). "We observed increased IFNB1, IL29/IFNL1, IL28A/IFNL2, IFNL3, RSAD2, and CXCL10 post infection." (PMID 33409274, 2020). "Il1β, Tnf, Il6, Ccl2, Ccl5, and Cxcl10 mRNAs were all increased in the CNS after infection." (PMID 32047134, 2020).
infection (continued). "The induction and persistence of CXCL10 with progressive infection has suggested that it might serve as a biomarker for assessing the clinical stages of SARS infection." (PMID 33613280, 2020). "Cxcl10−/− mice had the same viremia as wild-type animals, but fewer immune infiltrates and lower viral loads in footpads at the peak of arthritic disease (days 6–8 post infection)." (PMID 33147869, 2020). "As compared with polyI:C, AiV induced a lower level of antiviral gene expression, with huge differences in the level of IFNβ, Viperin, RIG-I, MDA5, IFN induced protein with tetratricopeptide repeats 3 (IFIT3) and CXCL10 between AiV infection and polyI:C stimulation." (PMID 32802187, 2020). "Mesangial cells infected with BKV showed an incremental induction of CXCL10 gene expression, which picks (6.7-fold) at 96 h and a more significant induction of IFNβ gene expression (28.3-fold) observed at 96 h post infection." (PMID 31252545, 2019). "Similarly, the L. major WT amastigotes continued to suppress CXCL10 protein while L. major Δgp63 infection significantly induced CXCL10 protein." (PMID 31440475, 2019). "qPCR analysis indicated that induction of antiviral genes including IFNB1, ISG56 and CXCL10 following infection with the DNA viruses HCMV, herpes simplex virus 1 (HSV-1), and vaccinia virus (VACV) was inhibited in HFF-UL42 as compared to empty vector-transduced control cells (HFF-Vec)." (PMID 31107917, 2019). "The authors also observed varying levels of CXCL10 induction over a time course of infection." (PMID 31533282, 2019). "In addition, CXCL10 has been noted to induce neuronal apoptosis, contributing to viral pathogenicity upon infection, including infection by West Nile virus (51, –, 53)." (PMID 31289185, 2019). "Therefore, we analyzed control and TIM-1-/- organs following EBOV GPΔO/rVSV infection for the chemokines, CXCL10 (IP-10) and CCL2 (MCP-1)." (PMID 31242184, 2019). "The cytokine response of CXCL10, however, confirms an active, productive infection, especially as the replication-deficient UV-RV did not elicit CXCL10." (PMID 31067687, 2019). "Elevated IP-10/CXCL10 levels rapidly identify a probable infection." (PMID 31485118, 2019). "To further examine the relationship of myeloid cell replication and the number of miR-142-3p binding sites to induction of chemokine mRNAs within the PLN, we quantified the level of Cxcl10 mRNA within the PLN after infection with each of EEEV mutants at 12 hpi." (PMID 31658290, 2019). "Also, we detected a significant secretion of interferon type III and the pro-inflammatory cytokine IP-10/CXCL10 upon infection with JEV." (PMID 31057517, 2019). "Further, seven human plasma chemokines were assessed, and fold-change in CXCL10 (HIV+ vs. HIV− plasma level) was significantly higher in HIV rapid progressors, with CXCL10 level during PHI negatively correlated with CD4+ T-cell counts at the 4-month-infection point." (PMID 31836011, 2019). "However, the infection with an African ZIKV strain led to monocyte differentiation to M1-type inflammatory responses with increased IFN-induced CXCL10 production." (PMID 31673117, 2019). "We tested whether the decrease in CXCL10 is due to a change in transcript by repeating the infection in LCLs and assaying both CXCL10 mRNA and CXCL10 protein." (PMID 31440475, 2019). "Interestingly, BKV infected differentiated podocytes showed a significantly smaller increase of CXCL10 and a marginal increase of IFNβ transcripts and at 96 h post-infection, as compared with undifferentiated podocytes." (PMID 31252545, 2019). "In mice, CXCL10 mRNA and protein are significantly induced after infection." (PMID 31440475, 2019). "Specific subsets of effector CD8+ T cells are recruited by CXCL10 after infection." (PMID 31440475, 2019). "Similarly, the cervical epithelial cell line A2EN produces CXCL10 at baseline, but this is significantly reduced after infection with C. trachomatis." (PMID 31440475, 2019).